IL33 (interleukin 33)
Diseases named in the same sentence as IL33 in open-access papers (continued):
Sharing a sentence is not in itself a finding about the gene and the disease.
vitamin D deficiency (6 papers, 2020 to 2024). A nutritional condition produced by a deficiency of VITAMIN D in the diet, insufficient production of vitamin D in the skin, inadequate absorption of vitamin D from the diet, or abnormal conversion of vitamin D to its bioactive metabolites. "Studies have shown that vitamin D deficiency can cause higher IL-33 levels, but taking vitamin D supplements can regulate IL-33 expression." (PMID 37759494, 2023). "The increased expression of the IL-33, TLRs, and M1 macrophages in VDDef swine suggests the presence of inflammation and increased cartilage loss associated with vitamin D deficiency." (PMID 34842603, 2021). "The results of this study revealed that vitamin D deficiency is associated with an increased expression of IL-33, IL-37, IL-6, TNF-α, TLRs, DAMPs, and MMPs, while vitamin D supplementation is associated with a decreased expression of the former." (PMID 34842603, 2021). "The results of this study suggest that vitamin D deficiency associates with increased expression of IL-33, a proinflammatory cytokine of the IL-1 family, and vitamin D supplementation results in decreased expression of IL-33 and inflammation." (PMID 34445530, 2021). "Vitamin D deficiency is associated with chronic inflammation and the increased secretion of IL-33." (PMID 34842603, 2021). "The presence of IL-33 and macrophages in vitamin D-deficient degenerating cartilage of microswine and the presence of macrophages in human osteoarthritic cartilage suggests a correlation between IL-33 and vitamin D deficiency in OA." (PMID 34842603, 2021). "As a consequence, it is conceivable that although both vitamin D and IL-33 in the bone environment exert protective effects against OP, in inflamed Pso skin and in PsoA, the deleterious effects of vitamin D deficiency and IL-33/ST2 axis activation potentiate each other." (PMID 33488605, 2020). "Therefore, in Pso-associated OP, the final effect of vitamin D deficiency and IL-33/ST2 axis overexpression is overall increased bone resorption due to the prevalence of proinflammatory and dysmetabolic processes." (PMID 33488605, 2020). "For example, IL-33 contributes to inflammatory reactions involving vitamin D deficiency but could also counteract some of its deleterious effects, mainly depending on the clinical context as well as on the cytokine and hormonal milieu." (PMID 33488605, 2020). "A vitamin D deficiency could somehow nullify the protective effect of IL-33 on bone through mechanisms that are still unclear." (PMID 33488605, 2020). "Further research could also consider the effect of TLR7 on other pathways involved in the amplification of the Th2 response, such as IL-13, IL-31, and IL-33 cytokines, vitamin D deficiency, and changes in the lung microbiome, in the context of chronic respiratory disease." (PMID 39769461, 2024). "The data are suggestive that vitamin D-deficiency is associated with the presence of inflammation and neointima formation, and that vitamin D supplementation reduces neointima formation, as well as the expression of the mediators of inflammation, including IL-33." (PMID 34445530, 2021).
bone cancer (5 papers, 2018 to 2022). A primary or metastatic malignant neoplasm affecting the bone or articular cartilage. "In addition, a previous study suggests that IL-33 plays an essential role in bone cancer pain, and its actions might be associated with inducing spinal upregulation of IL-1β and TNF-α." (PMID 29329586, 2018). "Taken together, these results suggested that IL-33/ST2 signaling participates in both acute and chronic pain, including radicular, arthritic, neuropathic, and bone cancer pain." (PMID 29329586, 2018). "Furthermore, activation of spinal IL-33 and ST2 has been reported to contribute to bone cancer pain." (PMID 32116550, 2020). "In addition, recent studies have proven that spinal IL-33/ST2 signaling plays a key role in the modulation of neuropathic pain and chronic bone cancer pain." (PMID 29329586, 2018). "Intrathecal administration of ST2 antibody suppressed the pain behavior, suggesting that IL-33/ST2 might play a critical role in cancer-induced pain and could serve as a putative target in bone cancer pain management." (PMID 30205617, 2018).
breast tumor (5 papers, 2014 to 2024). "Further, in breast tumors from patients with similar clinicopathologic characteristics, the presence of tumor necrosis was associated with lower expression of IL-33, IL-33R and VEGF." (PMID 26919112, 2016). "When looking at tissue specificity, our dataset revealed some breast tumor-specific characteristics, as IL-16, as well as some juxta-tumor-specific secreted molecules, as IL-33." (PMID 36539890, 2022). "IL-33 and IL-33R expression in tumor cells was lower in breast tumors with necrosis (p = 0.05 and p < 0.0001, respectively)." (PMID 26919112, 2016). "In patients with ER-positive breast tumors, the serum levels of IL-33 were 39.92 ± 13.97 pg/ml, and were significantly higher than in patients with ER-negative tumors, which were 32.79 ± 10.84 pg/ml, p = 0.033." (PMID 24778632, 2014). "In contrast, IL18, IL2RG, IL33 and MAPK10 were highly expressed in normal breast tissues, whereas they were expressed at low levels in breast tumor tissues (p < 0.001)." (PMID 38438469, 2024). "In order to correlate tumor necrosis with IL-33, IL-33R and VEGF expression, patients were divided into two groups based on the presence (20 patients) or absence (20 patients) of necrotic fields in breast tumor tissue." (PMID 26919112, 2016). "We next analyzed IL-33, IL-33R and VEGF expression and microvascular density (MVD) in breast tumors from 40 female patients with absent or present tumor necrosis." (PMID 26919112, 2016).
dry eye (5 papers, 2020 to 2024). "NLRP12/NLRC4 knockdown, GSDMD knockout, or the neutralization of mature IL-33 can obviously attenuate the damage to corneal epithelial cells, indicating that these molecules could be key targets for dry eye treatment in the future." (PMID 37250902, 2023). "IL-33 may contribute to disease severity by promoting type 2 helper cells (Th2) inflammation in the development of dry eye." (PMID 35628481, 2022). "Elevated tear levels of IL-33 were positively correlated with symptom scores but negatively correlated with tear film breakup time and Schirmer test in both non-SS dry eye and SS dry eye patients." (PMID 35628481, 2022). "In comparison to non-SS dry eye patients, levels of IL-33 in the tears of pSS patients were considerably higher." (PMID 35628481, 2022).
endometrial cancer (5 papers, 2016 to 2022). Primary or metastatic malignant neoplasm involving the endometrium (mucous membrane that lines the endometrial cavity). "IL-31 and IL-33 were significantly accumulated in cancer patients (p < 0.001) and higher levels correlated with higher grade of endometrial cancer (p < 0.001) which shows that IL-31 and 33 are associated with a more severe or progressed disease." (PMID 34951691, 2022). "EpCAM, TGM2, HE4, CA-125, and IL-33 measured in serum samples from 42 patients with endometrial cancer concerning clinicopathological factors." (PMID 33014844, 2020). "Recent studies showed that IL-31 and IL-33 protein levels were significantly elevated in sera from patients with endometrial cancer as compared to healthy controls." (PMID 30205617, 2018). "Because most patients received operation less than 18 months, the follow-up studies are still undertaken, and the correlation between IL-31/IL-33 and the overall survival time of the endometrial cancer patients is still under research." (PMID 27340318, 2016). "Interestingly, the sensitivity and specificity of IL-31 and IL-33 expression and detection were higher than the typical endometrial cancer biomarkers CAE, CA-125, and CA19-9." (PMID 30205617, 2018). "Thus, in this very first study linking endometrial cancer with IL-31 and IL-33, these interleukins could serve as better biomarkers for endometrial cancer diagnosis and prognosis." (PMID 30205617, 2018). "IL-6, Il-11, IL-31, IL-33, TNF-α, TGF-β1, SDF-1 and CXCR are involved in endometrial cancer cell growth and metastasis or involved in epithelial mesenchymal transformation (EMT) or associated with advanced disease." (PMID 34951691, 2022). "Comparison of the levels of EpCAM, TGM2, IL-33, CA125, and HE4 in pre- and post-operated endometrial cancer patients." (PMID 33014844, 2020).
gastric tumors (5 papers, 2019 to 2024). "IL-33 deficient gp130F/F/Il33−/− mice had reduced gastric tumour growth and reduced recruitment of pro-tumorigenic myeloid cells including key mast cell subsets and type-2 (M2) macrophages." (PMID 35677533, 2022). "To validate a functional contribution of IL-33 signaling as a master regulator of mast cell activation in the gastric tumor microenvironment, we generated IL-33 signaling deficient gp130FF; St2−/− mice." (PMID 31227713, 2019). "We provide evidence that tumor cell-derived IL-33 stands on the apex of a cascade by which mast cells, through recruitment of tumor-associated macrophages and their support of a vascular network, ensures the growth and maintenance of gastric tumors." (PMID 31227713, 2019). "Moreover, IL-33-activated MCs are associated with macrophage infiltration in gastric tumors." (PMID 39432538, 2024). "Collectively, we show that IL-33 is required for gastric tumour growth and provide evidence of a likely mechanism by which gastric epithelial-derived IL-33 drives mobilization of tumour-promoting inflammatory myeloid cells." (PMID 35677533, 2022). "Cell sorting of gastric tumours revealed that IL-33 chiefly localized to gastric (tumour) epithelial cells and was absent from tumour-infiltrating immune cells (except modest IL-33 enrichment within CD11b+ CX3CR1+CD64+MHCII+ macrophages)." (PMID 35677533, 2022). "In summary, we provide the first direct in vivo evidence supporting IL-33 as a cytokine driver of gastric tumour progression." (PMID 35677533, 2022). "IL-33 is overexpressed in human gastric tumours suggesting a role in driving GC progression although a causal link has not been proven." (PMID 35677533, 2022). "Collectively, these data indicate that tumor-derived IL-11 induces Il33 gene expression in gastric tumor cells, which triggers the secretion as well as the de novo synthesis of cytokines and chemokines by mast cells to produce a tumorigenic immune environment." (PMID 31227713, 2019). "Here, we provide evidence for IL-33 expression in gastric tumor epithelium to also be stimulated by an IL-11/Stat3 signaling cascade, which we and others have identified as an absolute requirement for effective growth of gastrointestinal tumors." (PMID 31227713, 2019). "A recent study identified an IL-33/mast cell/M2 macrophage axis promoting gastric tumorigenesis, where genetic deficiency in either ST2, mast cells or in vivo depletion of macrophages all restricted gastric tumour growth in gp130F/F mice." (PMID 35677533, 2022). "Here, using IL33 ligand genetic deficiency we affirm the role of IL33 signaling in GC progression via IL-33, and additionally provide evidence that unidirectional signaling by gastric (and tumour) epithelium-derived IL-33 via ST2 on mast cells is a critical component of gastric tumour progression." (PMID 35677533, 2022).
giant cell arteritis (5 papers, 2014 to 2021). "In keeping with our findings, recent studies have described a protective effect of the mutant allele of another IL33 gene polymorphism, rs7025417, in the risk of CAD in a Chinese population and also in the development of giant cell arteritis in Europeans." (PMID 26571131, 2015). "Increased expression of IL-33 and its receptor ST2, encoded by the IL1RL1 gene, has been detected in the inflamed arteries of giant cell arteritis (GCA) patients." (PMID 25409453, 2014). "In contrast, although IL-33 influences polarization of alveolar macrophages, there is limited evidence for a role of IL-33 in the formation of giant cells, although it may be a decisive pro-inflammatory cytokine contributing to the pathology of Giant Cell Arteritis." (PMID 33050608, 2020).
glomerulosclerosis (5 papers, 2019 to 2025). A hardening of the kidney glomerulus caused by scarring of the blood vessels. "Eosinophils were reported to be essential for the protective roles of ILC2s in the IL‐33‐treated adriamycin‐induced glomerulosclerosis." (PMID 40801800, 2025). "In B‐cell activating factor (BAFF)‐transgenic mice, IL‐33 exacerbated glomerulosclerosis in an ILC2‐dependent manner." (PMID 40801800, 2025). "IL‐33/ILC2s ameliorated adriamycin‐induced glomerulosclerosis through induction of eosinophils." (PMID 40801800, 2025). "The functional role of ILC2 for the reno-protective effect was shown in ILC-deficient Rag2−/− x Il2rcg−/− mice, where IL-33 administration failed to reduce adriamycin-induced inflammation and glomerulosclerosis." (PMID 33496881, 2021). "Adoptive transfer of splenocytes from IL‐33‐treated Rag1−/− mice into BAFF‐transgenic mice exacerbated IgAN deposition and glomerulosclerosis and increased proteinuria and serum creatinine." (PMID 40801800, 2025). "Along the same line, short-term IL-33 treatment was demonstrated to expand ILC2 and attenuated renal inflammation and glomerulosclerosis in adriamycin nephropathy." (PMID 33496881, 2021).
hepatitis B (5 papers, 2015 to 2022). "IL-33 has been reported to induce Tfh cells to enhance humoral immunity against hepatitis B virus infection." (PMID 35062695, 2021). "Landmark studies have detected IL-33 in patients with acute liver failure and in patients with hepatitis C and hepatitis B." (PMID 32486265, 2020). "However, reports have been made on the elevated levels of IL-33 in patients chronically affected by hepatitis B or C and on the Increased IL-33 levels in the plasma of patients with severe falciparum malaria with a protective role." (PMID 31849991, 2019).
keloid (5 papers, 2022 to 2026). An irregularly shaped, elevated mark on the skin caused by deposits of excessive amounts of collagen during wound healing. "Our results demonstrate that IL-33 levels are significantly elevated in the epidermis of keloid tissues, where it functions as an alarmin, promoting a chronic inflammatory response." (PMID 40230853, 2025). "Given that increases in IL-33 are frequently observed during inflammatory processes, our findings confirm that the epidermis is also inflamed and damaged during keloid progression." (PMID 40230853, 2025). "We highlight the IFN-γ-IL-33 loop as a central mechanism driving epidermal dysfunction and as a potential therapeutic target for keloid treatment." (PMID 40230853, 2025). "Elucidating the role of IL-33 in keloids provides novel insights into keloid formation and progression, as well as potential therapeutic targets." (PMID 40230853, 2025). "By elucidating the role of the IL-33/ST2 axis in keloid formation, this research provides valuable insights into potential therapeutic targets for managing this challenging condition." (PMID 40230853, 2025). "In this study, we first noticed an increased expression of IL-33 in the keratinocytes of keloid epidermis through histological staining." (PMID 40230853, 2025). "In this study, we identified that IL-33 expression is markedly elevated in the epidermis of keloids, with keratinocytes being the major source of IL-33." (PMID 40230853, 2025). "Here, we demonstrated that the enhancement of the IL-33/ST2 axis in keloid scars results from an IFN-γ-IL-33 feedback loop between keratinocytes and lymphocytes." (PMID 40230853, 2025). "Other cytokines, such as IL33, IL-13, IL-10 and IL-4 have also been noticed increased in keloids." (PMID 41556665, 2026). "The specific role of IL-33 was confirmed by the finding that IL-33 knockdown restored normal filaggrin and involucrin levels, suggesting that this cytokine drives the skin barrier dysfunction and chronic inflammation observed in keloids." (PMID 41155460, 2025). "We propose that epidermal IL-33 levels in keloid patients could serve as a biomarker to assess keloid severity and guide clinical decisions." (PMID 40230853, 2025). "In this study, we identified excessive expression of IL-33 in keratinocytes and ST2 in lymphocytes within keloid scars." (PMID 40230853, 2025). "In our study, blocking IL-33 via shRNA successfully reversed its inhibitory effects on keratinocyte maturation, highlighting the IFN-γ-IL-33 loop as a potential target for keloid treatment." (PMID 40230853, 2025). "Analysis of human keloid tissue showed a significant increase in IL-33 expression in the epidermis, but not the dermis, of both peripheral and interior keloid zones and non-lesional skin, compared to mature scars." (PMID 41155460, 2025).
Lewis lung carcinoma (5 papers, 2018 to 2024). "The importance of the IL-33/ST2/MyD88 axis for tumor inhibition was further confirmed in the CD8+ T cells-mediated tumor immunity through mDCs in a mouse model of Lewis lung carcinoma." (PMID 34209038, 2021). "IL-33 was reported to enhance programmed oncosis of ST2L-positive low-metastatic Lewis lung carcinoma." (PMID 29568370, 2018). "Interestingly, the antitumor activity of recombinant IL-33 (rIL-33) in the Lewis lung carcinoma (LLC) model was totally abrogated in the Sema4A knock-out (KO) mouse, indicating the relevance of the activation of DCs in the IL-33-mediated antitumor activity." (PMID 38881897, 2024).
myeloma (5 papers, 2018 to 2024). "Remarkably, while reduced myeloma cell proliferation was displayed after IL-12 and IL-18 administration in Rag-deficient animals, this was overturned when animals were treated with IL-33 together with IL-12 and IL-18." (PMID 35740879, 2022). "IL-33 treatment is also reported to induce a population of circulating inflammatory ILC2s and inhibit type 1 immunity against multiple myeloma." (PMID 35634336, 2022). "Moreover, diverse experimentation demonstrated that myeloma cell proliferation was linked with modifications of activity and phenotypic changes in bone marrow ILC2s, with an augmented presence of maturation markers and decreased cytokine response to IL-2/IL-33." (PMID 35740879, 2022). "The attendance of KLRG1hi ILC2s in ILC2-reconstituted Il2rg−/− Rag2−/− animals or in IL-33-treated wild-type animals, which were correlated with augmented eosinophil amounts but did not influence multiple myeloma progression." (PMID 35740879, 2022).
perinatal depression (5 papers, 2020 to 2025). "Higher cerebrospinal fluid IL-1b, IL-23 and IL-33 concentrations at pre-cesarean time were significantly associated with increased odds of perinatal depression." (PMID 38820411, 2024). "At the same time, higher CSF levels of IL-33 were observed in perinatal depression." (PMID 39922907, 2025). "Translationally, these findings imply that IL-33/ST2 signaling may represent a potent new immunotherapy for neonates with hypoxic ischemic encephalopathy." (PMID 32859229, 2020). "Interestingly, dysregulation of IL33 has been reported in ASD, SZ, BD, recurrent major depressive disorder (rMDD), and perinatal depression." (PMID 33276438, 2020).